INS (insulin)
Diseases named in the same sentence as INS in open-access papers (continued):
Sharing a sentence is not in itself a finding about the gene and the disease.
Insulin resistance (continued). "This review summarizes the evidence that supports the concept of endothelial regulation of obesity and the associated insulin resistance in fat, liver, and skeletal muscles, the classic targets of insulin." (PMID 28848738, 2017). "In contrast, favourable associations between SFRP5 and glycaemia, insulin, insulin resistance and other cardiometabolic risk factors were attenuated after adjustment for BMI." (PMID 28851362, 2017). "The dysregulation of certain miRNAs derived from diet-induced obesity has been implicated in the expression regulation of insulin signaling molecules and the pathogenesis of insulin resistance." (PMID 29159212, 2017). "Another barrier is insulin-induced weight gain leading to insulin resistance and an associated escalating insulin dose requirement, increasing blood pressure and LDL-cholesterol levels." (PMID 28770327, 2017). "While type 1 diabetes patients exhibit beta cell/insulin loss due to autoimmune reactions against the pancreas, type 2 diabetes develops as a consequence of insulin resistance that is frequent in obese patients." (PMID 28233125, 2017). "Several population-based studies have applied fasting insulin level or HOMA-IR as a marker of insulin resistance and have shown significant associations with cardiovascular events in non-diabetic individuals, independent of other risk factors." (PMID 28194232, 2017). "Impaired insulin secretion and peripheral insulin resistance cause hyperglycemia with increased hepatic glucose production in patients with type 2 DM." (PMID 28607575, 2017). "Since insulin resistance is one of the leading causes of the pathogenesis of cardiomyopathy, insulin signaling is one of the targets." (PMID 28620607, 2017). "A range of circulating factors are dysregulated early in the development of systemic insulin resistance, as either a cause or a consequence of disrupted cellular insulin signalling." (PMID 28852804, 2017). "The study by Madeira FB demonstrated that normal weight obesity increased the risk of metabolic syndrome, insulin resistance, and secretion of insulin and decreased insulin sensitivity." (PMID 29299442, 2017). "It is widely recognized that the primary defect in T2D is insulin resistance with a relative deficiency in insulin secretion." (PMID 28185153, 2017). "Type 2 diabetes (T2D) is characterized by insulin resistance and impaired insulin secretion, but the mechanisms underlying insulin secretion failure are not completely understood." (PMID 28585545, 2017). "In the current study, we showed that vitamin D deficiency via stably silencing 1α (OH)ase also caused insulin resistance in L02 hepatocytes, showing impaired insulin signaling and downregulation of GLUT4." (PMID 28978056, 2017). "The treatment with either Met or Saxa in the current study regained normal levels of both neurotransmitters, probably via alleviating the underlying pathology of insulin resistance and impaired insulin signaling." (PMID 28832656, 2017). "Nevertheless, long-term consumption of HFD causes obesity and insulin resistance possibly by reducing the interaction between insulin and insulin receptor substrate-1 (IRS-1) via diacylglycerol signaling." (PMID 29176994, 2017). "The experimental evidence shows that both, short-term diet with very high levels of fat and long-term diet with moderate fat content, cause many changes in the insulin signalling pathways and induce insulin resistance in the CNS." (PMID 28432486, 2017). "It is known that obese cats are insulin resistant, but weight loss normalizes this insulin resistance." (PMID 28629451, 2017). "T2D is characterized by high blood glucose levels and insulin resistance, which are caused by impaired insulin signaling in insulin-targeted tissues including the liver, muscle, and adipose tissues." (PMID 28061846, 2017). "These pathogenic IL-6+ Th17 cells then circulate to other insulin-targeted tissues (the liver and muscle), leading to insulin resistance." (PMID 28061846, 2017).
Insulin resistance (continued). "Together, these results suggest that IR degradation, caused by high levels of insulin, drives early podocyte insulin resistance, and that both the IR and nephrin are required for full insulin sensitivity of this cell." (PMID 28852804, 2017). "The importance of IDE in AD is well established as IDE is the only known enzyme that degrades β-amyloid proteins, which are a major cause of AD pathology, and that degrades used insulin which is the cause of insulin resistance." (PMID 28070499, 2017). "Increased insulin secretion, concomitant with the loss of pulsatile release, is associated with development of insulin resistance and obesity." (PMID 28798351, 2017). "Considering that insulin resistance is associated with insulin hypersecretion by β-cells, we next examined serum insulin levels and histopathological changes of pancreatic islets." (PMID 28736524, 2017). "Since impaired glucose tolerance is a pre-diabetic state of hyperglycaemia that is associated with insulin resistance, we quantified the volume of insulin secreted by DIO zebrafish." (PMID 28469250, 2017). "Oral antidiabetic agents should however not be regarded as a cause of obesity, as they were added to insulin with the aim of reducing obesity and insulin resistance." (PMID 28588898, 2017). "In some studies, retinal arteriolar narrowing and impaired microvascular perfusion have been suggested to delay the access of glucose and insulin to target tissues, which leads to insulin resistance—a major mechanism underlying type 2 diabetes." (PMID 28100181, 2017). "Null deletion or liver-specific inactivation of Ceacam1 in mice causes a defect in insulin clearance, insulin resistance, steatohepatitis, and visceral obesity." (PMID 28396653, 2017). "Fat cells respond differently to insulin, depending on factors such as their size, and a positive association has been shown between adipocyte size, fasting insulin levels and insulin resistance (HOMA-IR)." (PMID 28346464, 2017). "As elevated fasting insulin level is an indication of insulin resistance, RORαLKO mice predisposed to severe insulin resistance than RORαf/f mice." (PMID 28757615, 2017). "A central feature of T2DM is hyperglycemia, as a result of excessive hepatic glucose production, insulin resistance, and deficient secretion of pancreatic insulin." (PMID 28635632, 2017). "Previously, it was suggested that leptin and insulin levels, and insulin resistance have different associations with obesity." (PMID 29088261, 2017). "Accordingly, the results of our study show the possibility that, while FABP4 is important for the pathophysiology of insulin resistance, it is likely to be associated with the insulin secretion in T2DM." (PMID 28654680, 2017). "Insulin resistance accompanies many wasting conditions, and disrupted oxidative metabolism has been implicated in decreased skeletal muscle insulin sensitivity." (PMID 29375734, 2017). "The progression from normal glucose tolerance to type 2 diabetes is characterised by bothan increase in insulin resistance and a decrease in insulin secretion caused byβ-cell dysfunction." (PMID 28290272, 2017). "SNPs associated with fasting insulin-based measures of insulin resistance have previously been linked to a reduction in subcutaneous adipose tissue and adverse metabolic profiles." (PMID 29081791, 2017). "In insulin resistance associated with prediabetes, the insulin secretory response increases as a compensatory mechanism." (PMID 29046729, 2017). "Our finding of improvements in insulin sensitivity despite increases in plasma fetuin-A levels is inconsistent with fetuin-A playing a major causal role in insulin resistance in humans." (PMID 28770230, 2017). "Polycystic ovary syndrome is caused due to elevated androgens in women and is related to insulin resistance and DM, which is a genetic disorder of insulin action." (PMID 28969020, 2017).
Insulin resistance (continued). "Merocvi and cols reported that SGLT2 inhibitors as monotherapy improve insulin sensitivity and reduce the progressive loss of beta-cell function and insulin resistance; unfortunately, limited long- term data are available." (PMID 28680862, 2017). "Insulin resistance is the prime risk factor to initiate the defects in insulin signaling pathways and glucose transport to cells." (PMID 28620607, 2017). "Among adolescents, Villa compared ovarian volume between 86 girls with PCOS and 48 controls, demonstrating that OV was associated with circulating insulin levels and markers of insulin resistance." (PMID 28620546, 2017). "Recent studies have shown that SOCS down-regulates insulin signaling and causes insulin resistance, indicating a close relationship between SOCS and DM, and SOCS is considered a potential therapeutic target in T2DM." (PMID 29228585, 2017). "Insulin resistance is associated with mitochondrial dysfunction due to reduced insulin-stimulated mitochondrial activity." (PMID 28883902, 2017). "Sugar-sweetened beverages are positively associated with body weight, and added sugars from liquid sources are associated with higher fasting glucose, higher fasting insulin, and higher β-cell dysfunction and insulin resistance." (PMID 29892467, 2017). "This study showed that exposure to 22 h of constant light dampened the patterns of GLP-1 and insulin release, in association with insulin resistance." (PMID 28257081, 2017). "IGF-I/IR traits that have been associated with CRC risk include IGF-I, IGFBP3, insulin, glucose, and homeostatic model assessment–insulin resistance [HOMA-IR] levels in this study." (PMID 29023587, 2017). "Insulin levels have profound effects on thermogenesis, and thermogenic impairment has been shown to be associated with insulin resistance." (PMID 29058611, 2017). "Despite the lack of difference in AKT signalling in the tissues examined, our data suggests a protective effect of macrophage Jak2-deficiency on HFD induced systemic insulin resistance along with reduced circulating glucose and insulin levels." (PMID 28794431, 2017). "Progressive development of insulin resistance observed at the early stage of type 2 diabetes causes an increase in blood glucose concentration (hyperglycemia) and compensatory rise of insulin levels." (PMID 28236091, 2017). "Experimental studies indicated that similar to skeletal muscle, hepatic, and adipose tissue, insulin resistance can develop in bone tissue, and that this compromised insulin signaling is associated with decreased bone remodeling." (PMID 29133833, 2017). "Increased serum levels of insulin caused by insulin resistance induce proliferative abnormalities, which are likely to cause breast cancer." (PMID 28178355, 2017). "Insulin resistance (IR), operationally defined as a reduction in insulin-mediated glucose metabolism, is commonly associated with obesity, ageing, male gender and physical inactivity, and precedes and predicts Type 2 Diabetes Mellitus (T2DM)." (PMID 28777829, 2017). "Concerning carbohydrate homeostasis, Q1 patients were characterized by greater insulin resistance, poorer insulin secretion, and more pronounced BCF loss." (PMID 28899393, 2017). "Nevertheless, we have shown that the bioactive leptin levels were strongly associated with selected insulin secretion and insulin resistance indices superior to immunoreactive leptin levels." (PMID 28542631, 2017). "Our previous report documented that oxidative stress inhibited insulin-stimulated Akt and endothelial nitric oxide synthase (eNOS) activation in obesity-associated insulin resistance." (PMID 29267310, 2017). "This “normalizing” effect of weight loss on insulin sensitivity, already described in several publications on cats, is comparable to the reversal of insulin resistance by weight loss as described in humans." (PMID 28629451, 2017).
Insulin resistance (continued). "In univariate analyses, vaspin plasma level positively associated with age (r = 0.215, p = 0.003), adiponectin, insulin, homoeostasis model of assessment for insulin resistance index and waist–hip ratio in the whole population." (PMID 27604490, 2017). "Stratifying by the lifestyle modifiers, we assessed the effects of IGF-I/IR traits (fasting total and free IGF-I, IGF binding protein-3, insulin, glucose, and homeostatic model assessment–insulin resistance) on CRC risk as a mediator or influencing factor." (PMID 29023587, 2017). "Adipocyte differentiation is implicated in improving insulin sensitivity and impairment with insulin resistance." (PMID 29231905, 2017). "Reversing of these harmful effects by the use of insulin-sensitizing drugs like Met and Saxa suggests their involvement in alleviation insulin resistance as the underlying pathology of AD and hence their potential use as anti-dementia drugs." (PMID 28832656, 2017). "The pathogenesis underlying type 2 DM is characterized by insulin resistance and impaired insulin secretion." (PMID 28162091, 2017). "Body mass index, glycated hemoglobin, serum glucose and insulin concentrations, and homeostatic model assessment of insulin resistance were negatively associated with SMC." (PMID 28304338, 2017). "Insulin resistance has been associated with aberrant splicing of the insulin receptor, however post-receptor defects in insulin signalling have been suggested and cannot be excluded." (PMID 28915272, 2017). "Impaired fetal nutrition in late gestation has been linked to insulin resistance and type 2 diabetes in adulthood through permanent changes in the function of pancreatic beta cells or in the sensitivity of the tissues to insulin." (PMID 28064359, 2017). "In ob/ob mice, because insulin section is increased to compensate for the peripheral insulin insufficiency caused by insulin resistance, these animals develop hyperinsulinemia compared with normal +/+ mice." (PMID 29215553, 2017). "Obesity is frequently linked to insulin resistance, high insulin levels, chronic inflammation, and alterations in the behaviour of CD4+ T cells." (PMID 28651594, 2017). "During summer, early pregnancy energy (kcal) was associated with a negligible reduction in late pregnancy insulin resistance (−0.1%), while fat (g) was associated with a small increase in late pregnancy insulin resistance (1.4%)." (PMID 28775759, 2017). "Obesity is associated with both peripheral and hepatic insulin resistance where normal or elevated insulin levels have an attenuated biological response in these tissues." (PMID 28106818, 2017). "Accumulating evidence from human and animal model studies have linked vitamin D status to insulin secretion and insulin resistance, as both vitamin D receptor and 1- α-hydroxylase are present in the pancreatic β cells." (PMID 28423063, 2017). "Most of the correlates of insulin resistance remained similar except that high cholesterol was now associated with insulin sensitivity." (PMID 28767672, 2017). "As a matter of fact, in mice, miR-143 transgenic overexpression was shown to decrease insulin sensitivity impairing glucose homeostasis, while miR-143 deficiency was shown to protect from obesity-associated insulin resistance." (PMID 29200427, 2017). "If the enhanced ER localization and activity of PIP4k2b underlies MANF-mediated insulin resistance, reducing PIP4k2b should alleviate the impaired insulin response." (PMID 28924165, 2017). "Ad-Ptprg mice had a tendency to hyperglycemia, hyperinsulinemia, and reduced responsiveness to the glucose-lowering action of injected insulin suggesting that pathophysiological overexpression of hepatic PTPR-γ is sufficient to cause insulin resistance." (PMID 29180649, 2017). "This suggests that ATV or SQV caused insulin resistance and reduced glucose tolerance by impairing insulin signaling and that naringin improved insulin sensitivity in PI-treaded animals leading to improved glucose tolerance." (PMID 29121676, 2017).
Insulin resistance (continued). "Insulin resistance, measured as the homeostasis index (HOMA-IR) and the fasting insulin level, correlated with apoB, with the apoB : apoA-I ratio, and inversely with apoA-I supporting known association of insulin resistance with lipoprotein transport." (PMID 28473926, 2017). "Insulin resistance is defined as inability of the cells to reach the normal metabolic level under a certain concentration of insulin stimulation, accompanied by deficiency of IR or the components downstream of IR." (PMID 28928791, 2017). "Studies have shown that inflammatory factors such as TNF-α, IL-6, and monocyte chemoattractant protein-1 (MCP-1) interfere with the insulin signal transduction pathway and cause insulin resistance." (PMID 29164155, 2017). "Recently, it has been suggested that hepatic insulin resistance is associated with several molecules that are related to insulin signal modulation." (PMID 29089472, 2017). "According to the studies of other authors, GH causes relative insulin resistance by reduced peripheral glucose uptake, while ghrelin reduces glucose-stimulated insulin secretion, leading to the deterioration of glucose tolerance." (PMID 28596789, 2017). "The increase in FFA, as for example, in mitochondrial dysfunction linked to insulin resistance, is associated with increased serine phosphorylation of protein kinases involved in the insulin pathway." (PMID 29270126, 2017). "Insulin resistance caused by antiretroviral agents occurs by 2 mechanisms: direct interference with insulin signaling and/or as a consequence of mitochondrial dysfunction in adipocytes and/or muscle associated with lipodystrophy." (PMID 28293638, 2017). "Insulin is generally considered to be the main factor in the inhibition of lipolysis, but obesity is a well-known risk factor for insulin resistance, with increased lipolysis, and development of T2D." (PMID 28346464, 2017). "Inflammatory M1 macrophages cause adipose tissue inflammation and insulin resistance, whereas anti-inflammatory M2 macrophages ameliorate obesity-induced insulin resis-tance." (PMID 29040966, 2017). "Insulin resistance is associated with hyperinsulinemia and leads to adverse effects on arterial endothelium by several proposed mechanism including altered insulin signaling, endothelial dysfunction, and left ventricular diastolic function." (PMID 29216249, 2017). "Although the AD-like pattern in 18F-FDG images can be associated with increasing plasma glucose levels and higher insulin resistance, the relationship between the AD-like pattern and plasma insulin levels is still unclear." (PMID 28715453, 2017). "The pathway’s sensitivity to insulin can be blunted by many factors, such as NEFAs, causing insulin resistance." (PMID 28935866, 2017). "More recently, the combination of GLP-1 receptor agonists and insulin has been useful in tackling the weight gain associated with insulin and circumventing the need for high doses in the presence of significant insulin resistance." (PMID 28167928, 2017). "In 1994, Razay G. found that AD patients had peripheral hyperinsulinemia, insulin resistance and were overweight, describing the possible association between insulin signaling and AD." (PMID 28282917, 2017). "Previous studies indicated that rs926198 is associated with metabolic syndrome, fasting insulin levels, insulin resistance, hyperinsulinemic, hypertension and systemic sclerosis." (PMID 29190968, 2017). "We have identified novel structural and functional mechanisms underlying upstream effector complex formation during the anti-autophagic action by insulin, of which dysregulation underlies insulin resistance." (PMID 28740220, 2017). "Resistin, a hormone secreted by adipocytes, impairs glucose tolerance and insulin sensitivity in mice and has been associated with insulin resistance in humans." (PMID 28950020, 2017).